SLC25A16 (solute carrier family 25 member 16)
Description:
Mitochondrial inner membrane transporter that regulates coenzyme A homeostasis between cytosol and mitochondria. Could mediate the import of coenzyme A from the cytosol into the mitochondrial matrix. Alternatively, it could function in the export of 3'-dephospho-CoA from the mitochondrial matrix to the cytosol.
Synonyms: GDC; hGP; GDA; D10S105E; HGT.1; ML7; hML7
Tractability: Antibody: UniProt predicts a signal peptide or a membrane-spanning region. PROTAC: its protein half-life has been measured.
Gene: Protein-coding gene on chromosome 10 (68,473,079 to 68,527,523, reverse strand). Ensembl gene ENSG00000122912.
Subcellular location: Mitochondrion inner membrane
Subcellular location (Human Protein Atlas): Mitochondria
Pathways (Reactome):
Metabolism: Vitamin B5 (pantothenate) metabolism
Gene Ontology:
Molecular function: coenzyme A transmembrane transporter activity; transmembrane transporter activity; nucleobase-containing compound transmembrane transporter activity; organophosphate ester transmembrane transporter activity
Biological process: coenzyme A transport; mitochondrial coenzyme A transmembrane transport; pantothenate metabolic process; transmembrane transport
Cellular component: mitochondrial inner membrane; mitochondrion
Genetic constraint (gnomAD): Loss-of-function variants: 11 observed, 13.97 expected, observed/expected ratio (o/e) 0.79, 90% interval 0.5 to 1.3. The upper end of that interval is the gene's LOEUF score, 1.3, which puts it in group 5 of 6, group 1 being the genes least tolerant of losing a copy. Missense variants: 222 observed, 214.35 expected, observed/expected ratio (o/e) 1.04, 90% interval 0.93 to 1.16. Synonymous variants: 87 observed, 79.14 expected, observed/expected ratio (o/e) 1.1, 90% interval 0.92 to 1.31.
Homologues: Orthologues: chimpanzee SLC25A16 (99% identical), rabbit SLC25A16 (96% identical), pig SLC25A16 (94% identical), rat Slc25a16 (94% identical), mouse Slc25a16 (93% identical), guinea pig SLC25A16 (89% identical), dog SLC25A16 (79% identical), zebrafish slc25a16 (72% identical), tropical clawed frog slc25a16 (68% identical). Paralogues in human: SLC25A42 (36% identical), SLC25A12 (26% identical), SLC25A13 (26% identical), SLC25A24 (25% identical), SLC25A31 (24% identical), SLC25A5 (24% identical), SLC25A19 (24% identical), SLC25A25 (24% identical), SLC25A4 (24% identical), SLC25A6 (24% identical), SLC25A23 (23% identical), UCP2 (23% identical), and 37 more.
Diseases named in the same sentence as SLC25A16 in open-access papers:
SLC25A16 is named in the same sentence as 23 diseases in open-access papers, as found by Europe PMC text mining. Sharing a sentence is not in itself a finding about the gene and the disease. The quoted sentences say what the papers report.
Graves disease (3 papers, 2020 to 2024). Graves' disease is an autoimmune disorder that leads to overactivity of the thyroid gland (hyperthyroidism).It is caused by an abnormal immune system response that causes the thyroid gland to produce too much thyroid hormones. "The analysis identified several mitochondrial proteins downregulated by HFD, including the citrate carrier (SLC25A1), the dicarboxylate acid carrier (SLC25A10), a glutamate carrier (SLC25A22), and a carrier associated with Graves’ disease (SLC25A16)." (PMID 39111307, 2024). "SLC25a16 has been considered as a carrier of Grave’s disease, which causes hypothyroidism." (PMID 37108768, 2023). "SLC25A16 was called Graves’ disease carrier protein because it was picked up in an immunoscreen with antisera from patients with Graves’ disease." (PMID 32340404, 2020).
hypothyroidism (2 papers, 2018 to 2023). Abnormally low levels of thyroid hormone. "The Slc25a16 gene encodes a mitochondrial carrier associated with an autoimmune disease that results in hypothyroidism." (PMID 30537945, 2018). "On the other hand, hypothyroidism is thought to cause HBW, which may explain the association we found between SLC25a16 and higher birth weight, but this needs to be further explored." (PMID 37108768, 2023).
breast carcinoma (1 paper, 2025). "Further, we found that GNPDA1 and SLC25A16 were enriched in known targets of approved cancer drugs as potential genes associated with breast cancer." (PMID 40278313, 2025). "GNPDA1 overexpressed hypomethylation and SLC25A16 underexpressed hypermethylation in breast cancer cells were associated with poor prognosis in patients with breast cancer." (PMID 40278313, 2025). "Meanwhile, SLC25A16 hypermethylation is associated with poor survival in patients with breast cancer." (PMID 40278313, 2025). "Through a MethSurv analysis, GNPDA1 hypomethylation and SLC25A16 hypermethylation were associated with poor prognoses in terms of overall survival in breast cancer." (PMID 40278313, 2025). "Further, GNPDA1 and SLC25A16 were enriched in known targets of approved cancer drugs as potential genes associated with breast cancer." (PMID 40278313, 2025). "Using MetaCore, we examined the co-expressed genes for GNPDA1 and SLC25A16 from the cBioPortal and TCGA breast cancer data sets." (PMID 40278313, 2025). "According to our bioinformatics analysis results, GNPDA1 and SLC25A16 have much prognostic value—they play key roles in genetic alterations and signaling pathways in breast cancer." (PMID 40278313, 2025). "The result shows that breast invasive carcinoma (NOS) appears to have a much higher frequency of GNPDA1 and SLC25A16 (15,49%) than the other subtypes of breast carcinoma." (PMID 40278313, 2025). "Our comprehensive study revealed that GNPDA1 and SLC25A16 have prognostic value in patients with breast cancer." (PMID 40278313, 2025). "According to the DNA methylation analysis in the current study, GNPDA1 and SLC25A16 in a single CpG serve as prognostic biomarkers of breast cancer." (PMID 40278313, 2025). "According to the methylation levels, the cg00145118 of GNPDA1 and cg00203461 and the cg10590909 and cg16214034 of SLC25A16 had the highest prognostic value in patients with breast cancer (LR test p < 0.05)." (PMID 40278313, 2025). "Using the Methsurv web tool, a heat map demonstrated the significance scores of DNA methylation which predict expression levels of GNPDA1 and SLC25A16 in patients with breast cancer." (PMID 40278313, 2025). "The distribution of genetic changes for specific candidate genes revealed that GNPDA1 and SLC25A16 mRNA levels were elevated in approximately 5% of breast cancer samples." (PMID 40278313, 2025). "GNPDA1 and SLC25A16 exhibited significant expression in breast cancer tissues based on UALCAN analysis, where they were overexpressed and underexpressed, respectively." (PMID 40278313, 2025). "Meanwhile, compared to normal tissues, the SLC25A16 gene was considerably underexpressed in human breast cancer tissues." (PMID 40278313, 2025). "As a result of the gene list as input in MetaCore analysis, we discovered some interesting results regarding GNPDA1 and SLC25A16 in the development of breast cancer." (PMID 40278313, 2025). "Moreover, through a MetaCore functional enrichment analysis, GNPDA1 and SLC25A16 were associated with the BRCA1, BRCA2, and pro-oncogenic actions of the androgen receptor in breast cancer." (PMID 40278313, 2025). "This pathway was also significantly correlated with SLC25A16 in breast cancer development." (PMID 40278313, 2025). "GNPDA1 and SLC25A16 play important roles in the BRCA1, BRCA2, and pro-oncogenic actions of the androgen receptor in breast cancer development." (PMID 40278313, 2025).
nail disorder (1 paper, 2025). A disease involving the nail. "SLC25A16 is linked to diseases such as non-syndromic congenital nail disorders and isolated nail anomalies." (PMID 40278313, 2025). "Furthermore, SLC25A16 is linked to illnesses such as non-syndromic congenital nail disorders and isolated nail anomalies." (PMID 40278313, 2025).
cancer (5 papers, 2022 to 2025). A tumor composed of atypical neoplastic, often pleomorphic cells that invade other tissues. "Age, a family history of cancer, and alcohol consumption were associated with GNPDA1 and SLC25A16 based on the current data set and the GEO data set." (PMID 40278313, 2025).
tumor (5 papers, 2016 to 2026). "Statistically significant differences (p < 0.05) were observed in the expression of GNPDA1 and SLC25A16 between the normal and tumor tissues (left)." (PMID 40278313, 2025). "On the basis of tumor stage indicators, we found that in more advanced tumors, GNPDA1 and SLC25A16 mRNA expression tended to have more statistical significance (middle)." (PMID 40278313, 2025).
SLC25A16 also shares sentences with these, for which no sentence is quoted: infection (3 papers); Cognitive impairment (2); autoimmune disease (1); Autoimmunity (1); bacterial infection (1); breast invasive carcinoma (1); candidiasis (1); carcinoma in situ (1); disseminated candidiasis (1); lymphoepithelioma (1); migraine (1); multiple sclerosis (1); neurodegenerative disease (1); renal fibrosis (1); schizophrenia (1); urothelial carcinoma (1); viral infections (1).